L1CAM (L1 cell adhesion molecule)
Diseases named in the same sentence as L1CAM in open-access papers (continued):
Sharing a sentence is not in itself a finding about the gene and the disease.
cancer (continued). "Cell-surface glycosylation is upregulated in many different cancers, and a number of glycoproteins have been identified as ligands for galectin-3, including integrin β1, lysosome-associated membrane proteins 1 and 2, and the IgSF members carcinoembryonic antigen (CEA) and L1CAM." (PMID 22272201, 2012). "Consequently, elevated levels of L1CAM often indicate bad prognosis for cancer patients." (PMID 21541352, 2011). "While the effects of ROS on CAMs of other major families are more consistent, L1CAM is a notable example of an IgSF CAM that is differently regulated by ROS in neurons and cancer cells." (PMID 40710351, 2025). "The participation of L1CAM in the transition from EMT and resistance to chemotherapy further emphasizes its importance in cancer advancement." (PMID 40699746, 2025). "Collectively, our findings together with previous studies indicate that human L1CAM has the potential to serve as a CSC marker and as a therapeutic target for cancer treatment." (PMID 40429728, 2025). "In the clinic, the poor prognostic effects of ADAMTS1, L1CAM, and EGFR were observed only in HNSCC among 33 different cancer types suggesting that the ADAMTS1-L1CAM-EGFR axis plays a specific role in regulating OSCC progression." (PMID 38263290, 2024). "Our present results suggested that L1CAM is another downstream effector of ADAMTS1 that regulates EGFR activity and cancer progression." (PMID 38263290, 2024). "During the outgrowth of disseminated cancer cells in different organs, including the brain, the YAP activation was induced by L1CAM-dependent cancer cell spreading on the vasculature, through activation of β1 integrin and ILK." (PMID 37456245, 2023). "This idea is supported by the upregulation of neuronal receptors such as AMAPR, NMDAR, GFRα1, GFRα2, GFRα3, AChR, L1-CAM, and NCAM and their ligands, including glutamine, GDNF, NRTN, ARTN, and Ach, in cancers." (PMID 37566075, 2023). "As in other cancer cells, ectodomain shedding of L1CAM is mediated by ADAM10 and ADAM17, we investigated the expression of the soluble L1CAM ectodomain in cell culture supernatant after ADAM10/17 single and double knockdown." (PMID 36293469, 2022). "Further studies have been carried out in our institution to investigate the relationship between platelet–L1CAM signaling, systemic immune macroenvironment, TME, and cancer biological behaviors." (PMID 36387224, 2022). "CD171, also known as L1CAM, is expressed in nervous tissue and some cancer cells; it is known as a cell surface antigen in the central nervous system and plays an important role in neural development." (PMID 34576126, 2021). "The second marker, L1 cell adhesion molecule (L1CAM), is a membrane glycoprotein of the immunoglobulin family, crucially involved in cancer cell migration and adhesion." (PMID 34203959, 2021). "When GSK3β is inhibited by AKT, free β-catenin accumulate and translocate to the nucleus, ultimately activating downstream target genes such as cyclin D1, C-Myc, CD44, FN1, C-JUN, Slug, L1CAM, and MMP14; thus contributing to tumorigenesis and EMT of cancer." (PMID 34546849, 2021). "PTX enhances anti-L1CAM RIT effectiveness, blocking cancer cells in the radiosensitive G2/M cell cycle phase." (PMID 32257947, 2020). "Given the role of L1CAM in CSC, it is intriguing to envisage L1CAM-based strategies to target this cancer cell subpopulation." (PMID 32429448, 2020). "The CE7 epitope of L1-CAM (CD171) has been explored in the context of CAR-T therapy in NB tumors and other cancers, including lung, ovarian, and renal carcinomas as well as glioblastomas." (PMID 31191243, 2019). "As a CAM member, CHL1 and L1CAM another CAM have been reported in cancer development and metastasis in ovarian 17, breast 18, colon 19, pancreatic 20 and gallbladder 21 cancers." (PMID 31523184, 2019).
cancer (continued). "Mint3-mediated cancer cell proliferation depended on HIF-1, and further gene expression analysis revealed that the cell adhesion molecule, L1 cell adhesion molecule (L1CAM), was induced by Mint3 and HIF-1 in fibroblasts." (PMID 28504692, 2017). "The expression of L1CAM was present in 53 % of all cases, being more frequent in SCC (59 %) and other carcinomas (62 %), compared with 44 % among adenocarcinomas (p = 0.003)." (PMID 29207598, 2017). "Indeed, other than the homotypic cell adhesion shown in the present study, L1CAM can also mediate heterotypic interactions with activated endothelium and platelets by binding to multiple vascular and platelet integrins, which implies on promoting cancer cell extravasation." (PMID 25294816, 2014). "At first, L1CAM is a target gene of β-catenin-TCF signaling, which is an important cancer-related pathway." (PMID 22888955, 2012). "We determined that EPHB2 has significant interactions with several key proteins, including L1CAM, ABL2, KDM4A, BTF3, and SRC, suggesting that it may form a functional network critical to cancer progression." (PMID 41322437, 2025). "Additionally, L1CAM significantly contributes to epithelial‐mesenchymal transition (EMT) and cancer‐initiating cell (CIC) formation, further enhancing resistance to chemotherapeutic drugs." (PMID 39801758, 2025). "Soluble L1CAM was also detected in the blood of some patients with L1CAM-positive cancers compared with healthy controls or patients with L1CAM-negative tumors." (PMID 40870967, 2025). "Several candidates identified in our experiment, either in CuCl2-or CuCl2 and LA-treated groups, are directly involved in cancerogenesis (such as MEMO1, ATOX1, L1CAM, RABGGTA, MAP2K7 and others, and may be of potential interest for anti-cancer research." (PMID 39290994, 2024). "During this initial attachment stage, we did not observe differences between the L1CAM-positive or -negative cancer or FT cells." (PMID 36509990, 2022). "Meanwhile, cells can acquire enhanced proliferation and metastatic ability by overexpressing the neural cell adhesion molecule L1 (L1-CAM), and the expression of neutral endopeptidase is a necessary condition for the acquisition of L1 characteristics of cancer cells." (PMID 35847584, 2022). "L1CAM is highly expressed in PDAC cells, the expression levels of which are correlated with cancer progression, metastasis, and neural invasion via the induction of metalloproteinase-2 (MMP-2) and MMP-9 in cancer cells." (PMID 36077804, 2022). "By constructing in-vitro model of PNI, it was revealed that L1CAM secreted by Schwann cells attracts cancer cells into perineural niche via MAPK pathway and enhances expression of metalloproteinase (MMP) in cancer cells to facilitate penetration of extracellular matrix." (PMID 35223829, 2022). "The invasion of cancer cells to the perivascular environment relies on their motility, in which motility-involving molecules such as ARP2/3, L1CAM, serpins, CD44, CDC42, CXCR4, epidermal growth factor receptor (EGFR), as well as Wnt7 signaling, are critical players." (PMID 36119528, 2022). "On this account, L1CAM expression in the MELF component may stratify the prognosis and management in patients with uterine-confined, low-grade carcinomas." (PMID 35892892, 2022). "While the interplay between L1CAM and FGFR1 signaling has been extensively documented in the nervous system where it enhances neurite outgrowth, little information is available on its possible involvement in cancer cells." (PMID 34645505, 2021). "GSEA enrichment analysis suggested that the functions of L1CAM were significantly enriched in KEGG terms related to ECM receptor interaction, hematopoietic cell lineage, natural killer cell-mediated cytotoxicity, and pathways in cancer." (PMID 35003395, 2021).
cancer (continued). "Interestingly, we also observed upregulations of genes involved in axonal guidance like L1CAM, NRP1, semaphorins, and ephrins, emphasizing potential interactions of cancer cells and neuronal components of the stroma." (PMID 35008571, 2021). "To gain insights into the potential molecular mechanisms behind the role of L1CAM in CSC-like traits of ovarian CSCs, we tested the expression of several stem-cell and EMT-related genes known to be up-regulated in cancer stem cell populations in OC and in different other cancer types." (PMID 31952346, 2020). "Since L1CAM is not expressed in normal stem cells and it is present in the bulk population of cancer cells, anti-L1CAM RIT using Auger electrons and alpha-particle emitters would be a promising new option for ovarian CSCs therapy." (PMID 32257947, 2020). "By lowering the expression of these cancer-related markers and proteins commonly expressed in IBD patients (Muc18, Apoe, L1cam), WOL intervention might delay the onset of IBD-related CRC." (PMID 32258419, 2020). "The adhesion molecules such as L1 cell adhesion molecule (L1CAM) mediated attachment of cancer cells to the vascular surface is critical for vessel co-option, while the cancer cell motility is enhanced via activation of metabolic signaling pathways and cytoskeleton elements such as Arp2/3 complex." (PMID 33363174, 2020). "The depletion of L1CAM in cancer cells fails to co-opt brain capillaries and hence is unsuccessful in promoting metastatic outgrowth." (PMID 32059676, 2020). "Integrin β1 knockdown in MDA-MB-231 and A431 cells did not affect cancer cell proliferation itself, but abrogated Mint3/L1CAM-dependent cancer cell proliferation by MEFs." (PMID 28504692, 2017). "While the functional role of L1CAM in cancer vasculature has not been fully elucidated, the data available so far indicate a wide-spectrum function." (PMID 28134764, 2017). "We did not do an immunohistochemical evaluation of cancer specimens for L1CAM membranous expression; thus, we cannot say about the proportion of L1CAM-positive cancers in our group." (PMID 27832351, 2017). "It is noteworthy that there is a very high rate of concordance regarding the negative cases but a limited agreement in L1CAM positive cancers." (PMID 27233077, 2016). "Nonetheless, we found a highly significant correlation between qRT-CR and IHC with a high rate of concordance in the L1CAM negative samples but with noteworthy discordant results in positive cancers." (PMID 27233077, 2016). "High L1CAM expression was frequently observed at the invasive front of cancers with high vimentin and absent E-cadherin expression." (PMID 27833079, 2016). "L1 cell adhesion molecule (L1CAM, or CD171) is thought to be one of the many factors involved in the induction of Epithelial-to-Mesenchymal Transition (EMT), responsible for the gain of invasive properties of cancer cells." (PMID 27028855, 2016). "More specifically, CD24 could act from the cell membrane through BMI1 and/or Nanog to control the expression levels of MDR genes, CCND1 and DNA repair genes like L1CAM and NBS1 to combat cisplatin-induced toxicity and damage to the cancer cells." (PMID 27276062, 2016). "L1CAM expression does not appear to confer an aggressive phenotype to affected cancer cells." (PMID 41328908, 2025). "L1CAM depletion significantly reduced the ability of H2030-BrM3 and MDA231-BrM2 cells to spread on the surface of the capillary cavity and decreased the activity of brain metastasis of cancer cells, thereby mediating co-option and metastatic growth of brain capillaries." (PMID 38590656, 2024).
cancer (continued). "Importantly, the opposite correlation found with L1CAM in metastatic LUAD as it was previously thought of to facilitate migration and invasion by cancer cells in other cancers indicates that its role can be quite complex on a case-by-case basis within our current understanding." (PMID 39697539, 2024). "However, L1CAM expression was not restricted to neurons but was also upregulated during cancer progression (Gomes & Witwer, 2022; The Human Protein Atlas for L1CAM, n.d)." (PMID 38898558, 2024). "Thus, L1CAM can function both upstream and downstream of YAP/TAZ signaling in cancer cells." (PMID 37835395, 2023). "Thus, we hypothesized that L1CAM is involved in the regulation of pro-survival signaling pathways in FTSEC and cancer cell lines." (PMID 36509990, 2022). "To assess why superior in vitro performance of L1CAM-LS-28/ζ CAR T cells was not translated into superior anti-cancer activity in vivo, we monitored whether CAR T cell survival differed between the individual CAR T cell subsets after antigen exposure." (PMID 33801448, 2021). "However, very little and scattered information is available on the expression and function of L1CAM in CSC, although its contribution to cellular processes that are related to cancer stemness makes it a potential player in the pathophysiology of this cell subpopulation." (PMID 34645505, 2021). "ELDA analysis revealed that the cancer cell-initiating frequency of double-positive (1/316) was four times higher in comparison to the one of L1CAM+/CD133− (1/1245), three times higher than double-negative (1/1056) and six times higher than IGROV1 wild-type cells (1/1881)." (PMID 31952346, 2020). "Further analysis suggested that modulation of angiogenesis-related genes (including ANGPTL4, FN1, HSPG2, SRPX2, KLK5, L1CAM, Prr22, FOXJ1, IL24, and TRIM54) potentially contributes to anlotinib resistance, as anlotinib is a multi-targeted anti-angiogenesis drug for cancer therapy." (PMID 31572680, 2019). "Thus, L1CAM-L1CAM and L1CAM-integrin α5β1 interaction between cancer cells are not likely to be involved in the proliferation of MDA-MB-231 and A431 cells at least in vitro." (PMID 28504692, 2017). "Thus, L1CAM expression in Mint3 KO MEFs partially restored the proliferation of cancer cells, but did not affect angiogenesis in vivo." (PMID 28504692, 2017). "In the two mixed carcinomas with 50 % serous component, and 50 % endometrioid component, the serous component was strongly positive, whereas the endometrioid component was weakly positive, or L1CAM-negative." (PMID 26891628, 2016). "Additionally, cell adhesion proteins were identified, such as L1 cell adhesion molecule (L1CAM or CD171), a transmembrane protein and member of the immunoglobulin superfamily, which plays a major role in nervous system development, as well as cancer cell migration and invasion." (PMID 35629968, 2022). "L1CAM-positive cells may be found in the clear cell/papillary serous foci of the mixed endometrioid/non-endometrioid morphology cancers, which might facilitate identification of such small areas of differentiation within the endometrioid, L1CAM-negative background." (PMID 27832351, 2017). "L1CAM functions mostly in proliferation, migration, invasion, and survival through L1CAM homophilic interaction or heterophilic interactions with other cell adhesion molecules, integrins, or growth factor receptor, while the cellular properties are not homogeneous among different types of cancers." (PMID 28166242, 2017). "However, L1CAM has not been used to identify and isolate cancer stem cells." (PMID 22685459, 2012).
cancer (continued). "In this system, we showed lack of effector function in L1CAM-specific CAR T cells with 4-1BB co-stimulus, one of which was previously selected for a clinical trial because of proven anti-cancer activity after intratumoral delivery." (PMID 33801448, 2021). "Indeed, the present study has shown that all four cancer cell lines and the mesothelial cells are largely negative for CD6 and L1CAM." (PMID 36614319, 2023).
neurological disorders (16 papers, 2009 to 2025). "Mainly found in the nervous system, L1CAM is involved in several processes such as neuronal migration, neurite fasciculation and synaptic plasticity, and its mutations cause severe neurological disorders." (PMID 33167483, 2020). "L1cam (L1) is a cell adhesion molecule associated with a spectrum of human neurological diseases, the most well-known being X-linked hydrocephalus." (PMID 24489698, 2014). "Neuroglian (Nrg), whose vertebrate homologue L1-CAM has been implicated in neurological disorders, is also required for development of normal brain morphology in Drosophila." (PMID 23437330, 2013). "Mutation or deletion of L1CAM has been associated with an X-linked recessive neurological disorder, with at least 248 variants/mutations having been identified, but the roles of the variants, including the one in the proband, have not been studied in the immune system." (PMID 35967429, 2022). "L1CAM was initially hypothesized to be specific to the nervous system and has been implicated in numerous neurological disorders." (PMID 24660028, 2014). "The pivotal role of L1CAM in driving neuritogenesis results in a strong involvement in neurological disorders." (PMID 35052783, 2022). "Through the identification of a specific surface protein, L1 Cell Adhesion Molecule (L1CAM), NDEVs can be isolated from the blood and served as the platform of novel biomarkers identification of the neurological disease." (PMID 33344443, 2020).
neurodegenerative disease (8 papers, 2020 to 2025). A disorder of the central nervous system characterized by gradual and progressive loss of neural tissue and neurologic function. "The neural cell adhesion molecule L1CAM (L1) plays a functional role in the developing and adult nervous system and is thought to be linked to several neurodegenerative diseases." (PMID 33839994, 2022).
adenocarcinoma (7 papers, 2009 to 2025). A common cancer characterized by the presence of malignant glandular cells.
infection (4 papers, 2014 to 2024). The state of being infected such as from the introduction of a foreign agent such as serum, vaccine, antigenic substance or organism. "Analysis of the expression profiles in our study revealed that miR-449a and miR-449b were highly expressed at the early stage of infection, whereas the expression of their target genes L1CAM, MYO3B, SCIN, and STMN1 decreased." (PMID 38178220, 2024). "Western blot analysis indicated that the interfering efficiency was greatest in the Capan-2 cells 96 h after infection with ~75% reduction in L1CAM protein levels." (PMID 24660028, 2014). "The infection efficiency of Capan-2 cells with lentivirus-mediated sh-L1CAM was detected 96 h after infection by fluorescence microscopy." (PMID 24660028, 2014). "L1CAM protein expression in Capan-2 cells decreased following shRNA-L1CAM infection." (PMID 24660028, 2014). "Furthermore, the western blot analysis demonstrated that the L1CAM protein levels decreased in a time-dependent manner following infection." (PMID 24660028, 2014). "By contrast, the number of invasive Capan-2 cells after sh-L1CAM silencing was identified to be significantly lower 96 h after infection compared with the negative control (P<0.01)." (PMID 24660028, 2014).
brain disease (3 papers, 2022 to 2024). "For example, L1 neuronal cell adhesion molecule (L1CAM) was considered a BDEV marker, and attempts were made to analyze brain diseases via L1CAM-positive EVs in the blood." (PMID 36611896, 2022).
gynecological tumors (2 papers, 2020 to 2025). "The potential of L1CAM as a prognostic factor has received great attention from investigators working on gynecological tumors." (PMID 32429448, 2020).